HERC2P3 (HERC2 pseudogene 3)
Synonyms: D15F37S4; LOC283755
Gene: Transcribed unprocessed pseudogene on chromosome 15 (20,431,093 to 20,505,462, reverse strand). Ensembl gene ENSG00000180229.
Diseases named in the same sentence as HERC2P3 in open-access papers:
HERC2P3 is named in the same sentence as 4 diseases in open-access papers, as found by Europe PMC text mining. Sharing a sentence is not in itself a finding about the gene and the disease. The quoted sentences say what the papers report.
Alzheimer disease (1 paper, 2012). A progressive, neurodegenerative disease characterized by loss of function and death of nerve cells in several areas of the brain leading to loss of cognitive function such as memory and language. "The two genes LOC283755, also called HERC2P3, and PCYOX1L are not yet related to Alzheimer’s disease." (PMID 23066814, 2012).
tumor (2 papers, 2019 to 2021). "In this regard, HERC2P3 gene status could be considered a new candidate marker to evaluate the tumor response to RCT before surgery and the progression of disease in patients with LARC." (PMID 34202891, 2021). "The tenth gene “HERC2P3” contains a microsatellite locus that can precisely discriminate LUAD samples and non-tumor samples." (PMID 30761181, 2019).
HERC2P3 also shares sentences with these, for which no sentence is quoted: gastric cancer (1 paper); non-small cell lung carcinoma (1).